CYP4F35P (cytochrome P450 family 4 subfamily F member 35, pseudogene)
Synonyms: CYP4F-se8[6:7:8]
Gene: Transcribed unprocessed pseudogene on chromosome 18 (14,338,015 to 14,338,834, forward strand). Ensembl gene ENSG00000265787.
Diseases named in the same sentence as CYP4F35P in open-access papers:
CYP4F35P is named in the same sentence as 1 disease in open-access papers, as found by Europe PMC text mining. Sharing a sentence is not in itself a finding about the gene and the disease.
CYP4F35P shares sentences with these, for which no sentence is quoted: cancer (1 paper).